MTOR (mechanistic target of rapamycin kinase)
Diseases named in the same sentence as MTOR in open-access papers (continued):
Sharing a sentence is not in itself a finding about the gene and the disease.
cancer (continued). "A mathematical model of a minimal network was developed, and computer simulations were carried out, which suggest that the positive feedback loops of both KRAS and mTOR pathways have crucial roles in determining the GLUT1 transport and autophagy induction upon cancer development." (PMID 33925206, 2021). "As a research hotspot, the PI3K/AKT/mTOR pathway is not only important for signal transduction in normal cells, but also plays an essential role in tumorigenesis and cancer development." (PMID 34120414, 2021). "Quercetin has a broad range of biological activities including being anti-inflammatory, attenuating lipid peroxidation, inhibiting platelet aggregation, inducing cell death in cancer cells by enhancing autophagic flux and lysosomal activity, and suppressing PI3K/Akt/mTOR signaling pathways." (PMID 33768214, 2021). "Noteworthy, the efficacy of combinations of ET with mTOR, PI3K, and CDK4/6 inhibitors, the biological interplay between these pathways and the sensitization of cancer mutant cells led to the design of clinical studies investigating triplet combinations [,22,23,]." (PMID 33812267, 2021). "As reviewed herein, a vast body of evidence demonstrates that aberrant activation and/or dysregulation in the major components of the PI3K/Akt/mTOR signaling pathways are identifiable in different diseases, including most, if not all, human cancers." (PMID 33615993, 2021). "Delicaflavone, a novel anticancer agent, a biflavonoid from Selaginella doederleinii Hieron, induced ROS accumulation and inhibited the PI3K/Akt/mTOR signaling pathway, demonstrating the importance of studying ROS and the PI3K/Akt/mTOR pathway in the context of cancer." (PMID 34443626, 2021). "Overall, 13 cancer hallmarks were significantly upregulated in the MCL cells from patient B (the non-responder), including MYC, OXPHOS, BCR, mTORC1, cell cycle, and PI3K/AKT/mTOR signaling." (PMID 34001881, 2021). "Activated Akt could promote the migration, invasion and EMT of cancer cells, and inhibition of the PI3K/Akt/mTOR signaling could suppress tumour progression." (PMID 33901239, 2021). "Molecular studies in cancer showed that Wnt signaling controlled the activity of the mTOR pathway via GSK3β phosphorylation of TSC2, promoting the inhibitory function of TSC2 on mTOR activity." (PMID 34358226, 2021). "Moreover, alterations in the PI3K/Akt/mTOR axis are described as one of the major events in HCC, and exhibit as a crucial regulator of cancer cell proliferation and survival." (PMID 34367259, 2021). "Additionally, dual mTOR inhibitors were shown to arrest hypoxia- and TGFβ-mediated EMT in cancer cell lines." (PMID 35029792, 2021). "In this paper, we have endeavored to examine whether the combination of a PI3K/mTOR inhibitor, NVP‐BEZ235, or an Akt ATP‐competitive inhibitor, AZD5363, could sensitize cancer cells to the cytocidal activity of cisplatin or doxorubicin." (PMID 33338300, 2021). "Furthermore, KSHV dysregulates numerous metabolic sensors including mTOR, AMPK, CASTOR1 and sirtuins to maintain cellular energetic homeostasis during infection and in KSHV-induced cancers." (PMID 34579773, 2021). "In fact, the cancer cells have the ability of adaptation to hypoxia through the regulation of the PI3K/AKT/mTOR pathway and by the transcription factors HIF-1α and HIF-2α, whose protein expression and transcriptional activity are also regulated by mTOR." (PMID 33669301, 2021). "In addition to the PI3K/AKT/mTOR pathway representing a major driver in HNSCC and many other cancers, PI3K and mTOR can play fundamental functional roles in the innate and adaptive immune system." (PMID 33888713, 2021).
cancer (continued). "The results showed that 8 signaling pathways involved in ECM- receptor-interaction, pathways in cancer, Hedgehog signaling, TGF-beta signaling, JAK-STAT signaling, MAPK signaling, Wnt signaling, mTOR signaling were differentially enriched in the highly expressed phenotypes of LOX." (PMID 34595188, 2021). "mTOR inhibitor generally inhibits cancer cell proliferation via cell cycle arrest but does not induce cell death, which leads to the selective pressure to acquire mTOR inhibitor resistance." (PMID 33490663, 2021). "Interestingly, analysis of intracellular pathways potentially targeted by miR-495-3p, miR-376c-3p, and miR-6730-3p revealed several signaling cascades related to P2X7R activity and cancer, PI3K/Akt and mTOR included, and to migration and intravasation." (PMID 34789738, 2021). "Since PI3K/AKT mainly promotes the Cisplatin resistance in different tumors, suppression of this pathway through the RTK, PI3K, and mTOR inhibitors or specific miRNAs can be efficient methods to overcome the CDDP resistance and improve the quality of life in cancer patients." (PMID 37303943, 2021). "For example, the mTOR inhibitors Temsiro-Limus and Everolimus and the PI3K inhibitors Idelalisib and Copanlisib have been accepted by the FDA for Clinical treatment of patients with cancer." (PMID 34135756, 2021). "Further investigation into the biological function of the regulators identified several pathways, including TSC/mTOR, RTK, RAS/MAPK, PI3K/AKT, hormone ER, hormone AR, EMT, DNA damage response, cell cycle, and apoptosis pathways, that were significantly enriched in cancers." (PMID 34458283, 2021). "By enrichment analyses of gene function and protein-protein interaction network construction, we showed that these genes were enriched in several important cancer- or metabolism-related signaling pathways, including PI3K-AKT,RTK-RAS, Notch, Wnt, Hippo, mTOR, AMPK, and insulin signaling." (PMID 34805171, 2021). "ChREBP/mammalian target of rapamycin (mTOR) activation and AMP-activated protein kinase (AMPK) inhibition also represent likely key molecular events orchestrating metabolic reprogramming in GSDI during liver adenoma or carcinoma progression." (PMID 33922238, 2021). "Previous studies have observed that PHGDH inhibition induced autophagy in carcinoma cells but have attributed that effect to an mTOR-independent mechanism because of the lack of response to rapamycin treatment." (PMID 33503424, 2021). "Thus our data support the links between BMAL1 and mTOR pathway, which suggests BMAL1 regulation of protein synthesis and the role of circadian timing in cancer development." (PMID 32388500, 2020). "In addition, various rapalogues, such as everolimus and temsirolimus, pan-PI3K inhibitors, dual inhibitors targeting PI3K and mTOR, as well as mTOR and AKT signaling, have yielded promising pre-clinical results within a variety of cancer models." (PMID 33162811, 2020). "Among all the findings, down-regulation of CD274 caused by TXT and Ramucirumab in RELF-LC-A1 cells was unexpected results, because cellular stress response signals (i.e eIF2, NFkb, mTOR and OXPHOS) modulated by chemotherapeutic drugs are known to mostly up-regulate PD-L1 expression in cancer cells." (PMID 32993587, 2020). "Although the paradoxical role of autophagy in cancer treatment is still debated, we presume that the induced autophagy by inhibition of the PI3K/AKT/mTOR signaling pathway contributes to suppress cell proliferation, increase sensitivity to the GB treatment, and prolong survival time." (PMID 33123479, 2020).
cancer (continued). "To determine whether PI3K/AKT/mTOR signaling and PTEN are involved in GA mediated functions in ESCC, we examined the expression of related proteins in the cancer cells treated with GA." (PMID 32913452, 2020). "However, it was effective to reduce mTOR and NF-ƘB total protein amounts in MCF-7 cancer cells and induced apoptosis effectively together with bestatin." (PMID 32405891, 2020). "Current studies on targeting Rac and Cdc42 have identified compounds that are poised to emerge as leading antimetastatic drugs for combination therapy with cytotoxic cancer therapies and to overcome resistance to current therapies targeting RTKs and PI3-K/Akt/mTOR signaling." (PMID 32322580, 2020). "In addition, gene ontology (KEGG pathways) categories were enriched for pathways related to cancer, CML, Notch, ErbB, mTOR, Hippo, and MAPK signaling." (PMID 32532008, 2020). "In contrast, oncogenes may be activated by mTOR, class I PI3K (phosphoinositide 3‐kinases) and AKT (also known as protein kinase B), resulting in the suppression of autophagy and enhancement of cancer formation." (PMID 32935427, 2020). "The main mechanisms identified for obesity-mediated resistance of cancer cells to anticancer agents have been described in vitro or in mice and include alterations of the intracellular signaling pathway PI3K/AKT/mTOR, inhibition of cell cycle blockade and inhibition of apoptosis." (PMID 32795383, 2020). "It has been reported that PIK3R1 is differentially expressed in many human cancers and is closely related to tumor progression and metastasis, which make it an important therapeutic target through inhibiting the PI3K/AKT/mTOR pathway." (PMID 33192484, 2020). "Indeed, ginger and its derivatives were demonstrated to induce cancer cell death through modulation of the NF-κB, PI3K/AKT/mTOR, inflammation, cell cycle, angiogenesis, and apoptotic signaling pathways." (PMID 32795297, 2020). "For category 1, we identified a significant correlation of CCNE2-FOXM1 (10 cell line lineages, 17 patient cancer types) in cell cycle CTNNB1-SERPINE1 (eight cell line lineages, 17 patient cancer types) in EMT, and RB1-RPS6 (eight cell line lineages, 20 patient cancer types) in TSC/mTOR pathways." (PMID 32374631, 2020). "To test the hypothesis that HAR and PIP sensitize cells that are resistant to anti-cancer drugs, we first sought to determine the most effective concentrations for combined treatment with the PI3K/mTOR inhibitor BEZ235 and HAR or PIP." (PMID 33316942, 2020). "Moreover, hypoxia regulates EMT and cancer stemness in various cancers by targeting Notch, Wnt/β-catenin, Hedgehog, PI3K/mTOR and unfolded protein response (UPR) pathways." (PMID 33665161, 2020). "Additionally, mTOR pathway contributes to the synthesis of various secretions of α-SMA(+) CAFs, thereby eliminating the CAF-mediated drug resistance in cancer cells." (PMID 33292459, 2020). "Nevertheless, the most reliable targeted therapies against RAS-dependent cancers at the present are directed at PI3K (alpelisib), MEK (trametinib, cobimetinib and selumetinib), mTOR (everolimus) or at multiple signaling kinases (sorafenib), but not at RAS itself." (PMID 32545208, 2020). "Therefore, upregulated Rac and Cdc42 can drive malignant signaling during acquisition of resistance to cancer therapies targeting cell surface receptors, by acting downstream of therapy resistance mechanisms such as Ras/MAPK and PI3-K/mTOR signaling." (PMID 32322580, 2020). "Additionally, this drug has been demonstrated to regulate important cellular dynamics particularly during cancer progression (i.e., modulation of PI3K/Akt/mTOR activity) while promoting normal brain health through induction of BDNF." (PMID 33013390, 2020). "Intriguingly, Our data from cancer cell lines and animal experiments demonstrated that miR-135b down-regulated the JADE-1 to promote proliferation and suppress apoptosis of PCSCs via the AKT/mTOR pathway." (PMID 32351328, 2020).
cancer (continued). "Furthermore, the high four-gene score group also had enrichment for cancer aggressiveness-related gene sets, such as MTORC1 signaling, PI3K/AKT/MTOR signaling, DNA repair, unfolded protein response, hypoxia, and notch signaling." (PMID 33291601, 2020). "In cancer cells, the lack of (conditionally) essential amino acids determines the proteasomal degradation of the mTOR kinase, thus allowing pro-survival autophagy." (PMID 33364196, 2020). "Importantly, Niclosamide has been confirmed to target the Wnt/β-catenin, mTOR, STAT3, NF-κB, and Notch pathways has been widely investigated in multiple cancer types." (PMID 32284741, 2020). "The dual PI3K/mTOR inhibitors, such as NVP-BEZ235, GSK2126458, XL765, and SF1126, are introduced, since they are capable of inhibiting two vital signaling hubs (PI3K and mTOR) that stimulate the growth of cancer cells." (PMID 32887218, 2020). "We observed the PI3K-Akt signaling pathway, ErbB signaling pathway, mTOR signaling pathway, MAPK signaling pathway, transcriptional misregulation in cancer, pathways in cancer, and insulin signaling pathway were most commonly affected in the milk-siblings group in comparison to controls." (PMID 33133155, 2020). "These anti-cancer effects may potentially result from inhibition of EGFR and downregulation of the PI3K/AKT/mTOR, NF-κB, and STAT3 signaling pathways." (PMID 32328465, 2020). "In addition to diabetes, mTOR/S6K1-mediated feedback inhibition of IRS1 and by extension the oncogenic PI3K/Akt pathway poses drawbacks for cancer therapy and limits the cytotoxic effects of rapamycin-based therapeutic approaches." (PMID 32054043, 2020). "However, the antineoplastic cancer potential of metformin has also been assessed and it appears that this activity is unrelated to AMPK-dependent and -independent inhibition of mTOR." (PMID 33375360, 2020). "Thus, although the mTOR pathway is involved in almost every process of cancer, including cell growth, proliferation, metabolism, and immune response, the activation of AKT by mTOR inhibitors limits its clinical effectiveness." (PMID 32175074, 2020). "Thus, disrupting PI3K/Akt/mTOR signaling by PTEN leads to a dramatic decrease in survival and metastasis of cancer cells." (PMID 32756305, 2020). "Notably, we observed that the levels of p-AKT and p-mTOR were down-regulated in the cancer cells treated with 0.5 and 1 μM GA for 24 hours, while the expression levels of AKT and mTOR remained unchanged." (PMID 32913452, 2020). "Also, they can control abnormal growth and survival of cancer cells by activating various signaling pathways, including AKT/mTOR and MAPK pathways." (PMID 33024416, 2020). "Effectiveness of combining endocrine therapy with mTOR inhibitors has been tested in several trials, including the TAMRAD trial, a randomized phase 2 trial of tamoxifen with or without everolimus in postmenopausal women with AI-resistant, ER+, advanced cancer." (PMID 32351542, 2020). "Also, of note, miRNA-21, a circulating tumor biomarker for early cancer diagnosis, is capable of mediating the expression of Bcl-2 and PI3K/AKT/mTOR signaling pathway." (PMID 32076440, 2020). "In conclusion, our results demonstrate that the GOLPH3/AKT/mTOR axis is negatively regulated by miR-3135b resulting in apoptosis activation and a decreased proliferative capacity and cell cycle arresting of HCT-15 and SW-480 cancer cells." (PMID 32601379, 2020).
cancer (continued). "Importantly, recent studies have revealed that high levels of TRIM44 induce the epithelial-to-mesenchymal transition (EMT) in cancer cells and that TRIM44 promotes tumor initiation and progression by activating the PI3K/AKT/mTOR pathway." (PMID 32503466, 2020). "In vitro studies support the hypothesis that Trp depletion inhibits the master metabolic regulator mammalian target of rapamycin (mTOR) and protein kinase C (PKC-Θ) in cancer cells, which consequently enhances autophagy and Treg development, respectively." (PMID 32612606, 2020). "MTOR is an important target of AMPK, and much effort has been expended for treatment of cancer." (PMID 32014006, 2020). "The fact that PD-L1 protects cancer cells from immune-mediated cell death via activation of the PI3K/AKT pathway and mTOR supports the notion that dysregulated cancer cell-autonomous metabolism might represent a two-way barrier against antitumor immunity." (PMID 32630618, 2020). "Based on its normal biologic functions, it is obvious that pharmacological targeting the of PI3K/mTOR pathway as cancer treatment is unlikely to be devoid of on-target metabolism-related toxicities." (PMID 32033478, 2020). "In addition, emerging data have implicated frequent activation of mTOR with the progression of most cancers, including CRC3,4, which represents mTOR as a compelling therapeutic target for cancer treatment." (PMID 33067464, 2020). "Further, to investigate this association, we evaluated the correlation between SESN2 and mTOR pathway-related markers, including RPTOR, MTOR, and RHEB, by analyzing RNA expression data from cancer patients using the Gene Expression Profiling Interactive Analysis (GEPIA) database." (PMID 32899752, 2020). "Subgroups of 3–9 mice were assigned, in which the diet were implemented either with or without added rapamycin, an mTOR inhibitor and potential anti-cancer drug." (PMID 33270630, 2020). "RBM15B was enriched in aminoacyl tRNA biosynthesis (NES = 2.12, p = 0.011), mTOR signaling pathway (NES = 1.94, p = 0.023), Notch signaling pathway (NES = 2.10, p = 0.008), pathways in cancer (NES = 1.82, p = 0.049), and Wnt signaling pathway (NES = 1.86, p = 0.044)." (PMID 33362863, 2020). "The expression of PD-L1 in cancer cells is regulated by multiple signaling pathways, including NFκB, MAPK, mTOR, STAT, and c-Myc8,9, while PD-L1 protein undergoes degradation in proteasomes or lysosomes by multiple pathways, leading to increased effectiveness of cancer immunotherapy." (PMID 33159034, 2020). "The 76 related pathways included cancer pathways and disease pathways, most of which were related to signaling pathways, such as the PI3K-AKT signaling pathway, FoxO signaling pathway, mTOR signaling pathway, ErbB signaling pathway, AMPK signaling pathway, and HIF-1 signaling pathway." (PMID 32020871, 2020). "Given the critical role of mTOR in oncogenic EGFR signaling function, we considered the possibility that mTOR may promote TF expression in EGFR-mutant cancers." (PMID 32923403, 2020). "In addition, the mTOR inhibitor PP242 can restore EMT, increase the expression of PD-L1 in cancer cells, and restore the sensitivity of cancer cells to chemical drugs." (PMID 33117713, 2020). "Many cancer cells, including HCC, exhibit up-regulation of mTOR." (PMID 32547320, 2020). "The preclinical data presented here strongly support the clinical testing of PI3K/mTOR pathway inhibitors, in particular p110α-selective PI3K inhibitors such as alpelisib, in patients with ER+/HER2−breast cancer experiencing disease progression on CDK4/6-based therapies." (PMID 32795346, 2020).